NGF (nerve growth factor)
Diseases named in the same sentence as NGF in open-access papers (continued):
Sharing a sentence is not in itself a finding about the gene and the disease.
tumor (continued). "On the other hand, NGF is a complex molecule that has a pro-inflammatory and pro-tumoral role but also a negative feedback able to inhibit excessive inflammatory responses and tumor progression." (PMID 38392180, 2024). "Notably, both macrophages and tumor cells possess the capability to express NGF, which in turn can induce the growth and extension of nerve fibers." (PMID 38567163, 2024). "Moreover, research targeting NGF and its receptors has revealed new ways to regulate the interactions between neurons and CSCs within the tumor microenvironment, offering possibilities for developing new therapeutic strategies." (PMID 38567163, 2024). "In conclusion, this report may provide a comprehensive overview of the multifaceted role of NGF as a component of the inflammatory phenomena in tumor cell growth and death, offering new perspectives on its potential as a therapeutic target in cancer treatment." (PMID 38392180, 2024). "However, the paradoxical effects of NGF in cancer extend beyond its oncogenic potential, as accumulating evidence suggests its involvement in promoting tumor cell death in specific cellular contexts." (PMID 38392180, 2024). "In its function as a kinase, TrkA orchestrates various NGF effects, including neuronal differentiation, neural proliferation, nociceptor response, the inhibition of programmed cell death, cell metastasis, and tumor progression." (PMID 38816365, 2024). "Moreover, evidence suggests that pancreatic ductal adenocarcinoma (PDAC) cells secrete NGF to promote tumor innervation." (PMID 39385213, 2024). "Larotrectinib presented anti-tumor effects through the inhibition of NGF-promoted tumor growth." (PMID 39247831, 2024). "In contrast, NGF modulates tumor promotion and potentially dampens the need for an immune response." (PMID 39429264, 2024). "On the other hand, evidence suggests that NGF can promote endothelial cell proliferation and angiogenesis by stimulating pro-angiogenic factors, facilitating the delivery of oxygen and nutrients to the tumor cells, and promoting tumor growth and metastasis." (PMID 38392180, 2024). "Moreover, in the field of tumor therapy, monoclonal antibodies against NGF not only effectively suppress tumor growth but also provide analgesic effects." (PMID 38567163, 2024). "Furthermore, PD‐1 mAb acts synergistically with the NGF‐NGFR communication to suppress tumor progression in both mouse models and HCC patients." (PMID 38204220, 2024). "Therefore, to understand the role of NGF‐NGFR communication in the anti‐tumor immunotherapy with PD‐1 mAb, the BALB/c nude mice were injected subcutaneously with the NGF‐sh‐Lv‐infected Huh7 cells." (PMID 38204220, 2024). "Targeting neural regeneration pathways, especially those involving NGF, may inhibit tumor progression, as cancers such as pancreatic and breast cancer promote nerve growth to facilitate metastasis." (PMID 39492832, 2024). "The advancements in the single‐cell sequencing technology were used in the present study, and the results revealed a unique NGF‐NGFR communication and precisely elucidated the cell types involved in the NGF‐NGFR communication in the tumor tissues of HCC patients." (PMID 38204220, 2024). "NGF also plays a role in cancer cachexia and tumor progression and is highly elevated in OSCC." (PMID 39099944, 2024). "Indeed, in many human GBM cells (such as U-87), NGF exerts a mitogenic effect through the interaction with its receptor Trk, localized on the surface of tumor cells." (PMID 39682125, 2024). "The oral administration of larotrectinib significantly inhibited NGF-mediated tumor growth." (PMID 39247831, 2024). "Furthermore, we shed light on the multifaceted role of NGF in promoting tumor angiogenesis, its influence on EMT, and its ability to modulate the immune response within the TME." (PMID 38392180, 2024).
tumor (continued). "In some cases, NGF may promote the expansion of regulatory T cells (Tregs), which can suppress the activity of cytotoxic T cells and dampen the anti-tumor immune response." (PMID 38392180, 2024). "Furthermore, NGF upregulation correlates with larger tumor size, advanced clinical stage, greater tumor thickness, and close or positive section margin in oral SCC and ACC." (PMID 39906323, 2024). "Importantly, NGF secreted by tumor cells interacts with NGFR present on the membranes of the infiltrated T cells, thereby promoting the proliferation through the activation of mitotic spindle signals." (PMID 38204220, 2024). "Other preclinical studies found that targeting NGF had a satisfactory anti‐tumor effect." (PMID 36039037, 2023). "In the PDAC stage, the amount of NGF in tumor cells can increase up to seven-fold." (PMID 37834436, 2023). "We hypothesized that this tumor growth is accelerated and mediated by a constant loop-like transcription or translation regulation of effector genes of the growth factor family: NGF, NT3/4, EGF, and PDGF." (PMID 37965463, 2023). "However, tumor cells induce and drive the generation and growth of axons and nerves by secreting high levels of NGF." (PMID 37007073, 2023). "Thereby, binding to ADBR2 leads to an increase in tumor growth and overexpression of NGF." (PMID 37834436, 2023). "Ro additionally inhibits the nerve growth factor (NGF), another tumor driver." (PMID 37620963, 2023). "NGF is an essential neurotrophic factor that induces the growth of sensory and sympathetic nerves, which is highly expressed in tumor cells and various immune cells in the tumor microenvironment (TME)." (PMID 37007073, 2023). "Moreover, a study revealed that the ectopic expression of NTRK1 induced nerve growth factor-dependent cell death in the tumor of the nervous system via autophagy." (PMID 37907480, 2023). "Microdissection studies demonstrated that both PDAC cells and nerves produce NGF and both express the corresponding receptors, so that a reciprocal interaction may be established over the time course of tumor disease." (PMID 37834436, 2023). "This supports the hypothesis that tumor-released NGF stimulates neuron growth and the innervation of the tumor." (PMID 36499024, 2022). "In various malignancies, NGF has been reported to stimulate tumor growth and metastasis." (PMID 35457078, 2022). "One consideration is that the pro‐nociceptive ligands being produced during tumour progression and leading to generation of pain signals (e.g., nerve growth factor, endothelin‐1, prostaglandin E2, etc.)may also be promoting aggressive tumour behaviours." (PMID 35257492, 2022). "However, it has been found only recently that cancer cells produce nerve growth factor and therefore stimulate the ingrowth of new axons into the tumor tissue." (PMID 34953048, 2022). "Increased NGF production, in turn, exacerbates tumor innervation." (PMID 36230914, 2022). "Notably, antagonizing ADRB2 or blocking TRK1, a receptor for NGF, significantly delays the tumor growth in murine models." (PMID 36139512, 2022). "It was reported that NGF regulated the function of several types of tumor cells through TrkA." (PMID 36522730, 2022). "Further, the results revealed that NGF inhibition could reduce tumor volume and invasive nerve diameter." (PMID 36285300, 2022). "In search for a link between these three apparently unlinked items, it might be argued that NGF and other neurotrophins secreted from PC cells or CAFs sustain tumor survival and aggressiveness through a paracrine loop, as it occurs in breast cancer." (PMID 35222290, 2022). "GNCs that constituted by a straight but effective method endowed the complex with a high loading capacity of siRNA which significantly reduced NGF expression as well as the neurite sprouting, and eventually inhibited the tumor growth by activating a variety of downstream protein kinases." (PMID 34466734, 2022).
tumor (continued). "NGF may contribute to PNI by restraining the apoptosis of tumor cells, promoting the hyperplasia of nerves, and specifically enhancing the NGF and TrkA interaction." (PMID 35109895, 2022). "Remarkably, NGF-induced neurons often express tyrosine hydroxylase, further supporting the existence of a positive pressure of sympathetic adrenergic signaling on cancer evolution through increased tumor aggressivity and treatment resistance." (PMID 36499024, 2022). "Mice treated with C-87 exhibited lower concentrations of the following pro-inflammatory cytokines in the tumor paw compared to vehicle-treated tumor-bearing mice: TNFα (p < 0.05), NGF (P < 0.05), IL1β (P < 0.05), IL4 (P < 0.05), IL28β (P < 0.001), IL33 (P < 0.01), MIP3α (P < 0.01)." (PMID 33469141, 2021). "Indeed, tumor cells have the ability to produce substances that stimulate the growth and survival of nerve cells, such as the Nerve Growth Factor, or NGF, which belongs to a class of growth factors called neurotrophins." (PMID 33946706, 2021). "NGF can also promote tumor cell proliferation, survival and metastasis in breast cancer." (PMID 34722510, 2021). "To determine whether the NGF plays a role in tumor growth, we next analyzed cell proliferation effects in LNCaP and C4-2 cells with NGF overexpression." (PMID 33398073, 2021). "Meanwhile, serine deprivation led to selective secretion of NGF, suggesting that nerve–tumor crosstalk via amino acids may influence PNI." (PMID 34885121, 2021). "The Ro 08-2750 group could reduce the tumor formation compared to the normal controls, while NGF with verteporfin injection abrogated the NGF-enhanced tumorigenicity in vivo." (PMID 34722240, 2021). "NGF plays an important role in tumor cell proliferation, migration and survival." (PMID 34283074, 2021). "Indeed, it is clear that many types of tumors have the potential to secrete NGF, which induces peripheral nerve infiltration into the tumor microenvironment, thereby promoting tumor growth and metastasis." (PMID 33398073, 2021). "Furthermore, tumor xenograft animal models were established to observe the important role of NGF in vivo and its regulatory mechanisms." (PMID 34722240, 2021). "Further, both in vitro and pre-clinical in vivo studies revealed the prominent role of anti-NGF therapies in promoting tumor regression and PNI inhibition, thereby suggesting that NGF may become a relevant target for future anticancer therapies." (PMID 34503281, 2021). "The overexpression of NGF significantly increased the tumor growth in the tibia." (PMID 34283074, 2021). "Thus, there is an element of reciprocal interaction between nervesand tumour cells driving tumourigenesis; Schwann cells migrate towards tumourcells while prostate tumour cells in turn recruit nerves via pro-NGF." (PMID 33465324, 2021). "Knockdown the expression of NGF in vitro and in vivo to suppress tumor growth." (PMID 35127533, 2021). "NGF induces tumor angiogenesis by enhancing endothelial growth, migration and permeability." (PMID 33324652, 2020). "For example, NGF was correlated with lymphatic metastasis, tumor stage, and N stage." (PMID 32235004, 2020). "These cells can also synthesize, store, and release consistent amounts of NGF, which suggests that NGF may influence the anti-tumor immune response." (PMID 32508884, 2020). "Inhibition of NGF with siRNA significantly reduces tumor progression and angiogenesis in breast cancer, while overexpressing TrkA increases tumor development and angiogenesis." (PMID 33324652, 2020). "Tumor cells further express NGF, which has similar angiogenic effects as VEGFA." (PMID 33324652, 2020). "In the balance function of tumour microenvironment, we propose that NGF/TrkA could serve as an effective and potential therapeutic target for PC patients." (PMID 32294802, 2020). "Our results showed that NGF increased the mRNA of VEGF 121 in non-tumour and EOC cells (p < 0.05)." (PMID 33081077, 2020).
tumor (continued). "Thus, NGF release from tumors increases the sympathetic innervation of tumors, which drives increased tumor aggression and treatment resistance." (PMID 33322770, 2020). "Under pathological conditions, NGF is produced by tumor, inflammatory, and immune system cells." (PMID 31801267, 2019). "Indeed, the most relevant known effects of NGF and its receptors on key cellular substrates and molecular mechanisms of the tumor immune surveillance are reported here below." (PMID 31812953, 2019). "NGF might improve cell survival after a cell cycle arrest in tumor cell nests (or cell culture), which contain sufficiently high number of cells with NTRK1." (PMID 29904026, 2018). "NB tumours expressing TrkA have a positive prognosis due to a higher chance of spontaneous regression or differentiation of the tumour as a result of the interaction of TrkA and nerve growth factor (NGF)." (PMID 29315268, 2018). "p75NTR in HNSCC might be related with NGF-independent therapy resistance, while NTRK1 might transduce a survival signal of NGF and contribute in this way to improved tumor cell survival after cell cycle arrest." (PMID 29904026, 2018). "NGF seems to be sufficiently produced by normal epithelial cells and by tumor cell nests." (PMID 29904026, 2018). "TrkAIII transfectants also exhibit elevated expression of the NB tumour stem cell-markers CD117, SOX2, Nestin and Nanog, indicating that TrkAIII not only blocks NGF/TrkA-induced NB cell differentiation but also promotes a more NB tumour stem cell-like phenotype." (PMID 29914559, 2018). "The antitumor effect of NGF was accompanied by an increase in the lymphocytic infiltration of the tumor tissue, the level of interleukin 1β and tumor necrosis factor α in the serum, as well as the activity of lactate and succinate dehydrogenases in tumor cells." (PMID 28878143, 2017). "There are some data about the involvement of NGF in carcinogenesis, and mammalian NGF may promote or suppress tumor growth, depending on the tumor type." (PMID 28878143, 2017). "It is highly plausible that additional tumour derived factors are associated with this as NGF secretion is not significantly different between MCF-7 and MDA MB 231 cells." (PMID 29100335, 2017). "We confirmed the distribution of NGF in orthotopic tumours by IF staining." (PMID 28440296, 2017). "This supports the notion that NGF drives expansion of the sensory nerve fibres in tumours." (PMID 29100335, 2017). "The NGF antitumor mechanism may cause an increase of lymphocytic infiltration in the tumor, a rise in the levels of IL-1β and TNF-α in the serum of tumor-bearing mice, and an increase in aerobic glycolysis." (PMID 28878143, 2017). "Thus, the inhibition of tumor growth after the NGF treatment was accompanied by increased activity of both LDH and SDH." (PMID 28878143, 2017). "NGF increased the lymphocytic infiltration in the tumor compared to control samples." (PMID 28878143, 2017). "The copy number gains observed for NGF and KCNH6 also have a low probability of being driver mutations of DFT1 as they are not on a chromosome posited to be initially involved in the formation of the tumour." (PMID 28821767, 2017). "We examined the NGF knockdown in orthotopic tumours with siRNA treatments." (PMID 28440296, 2017). "Therefore in an NGF rich environment, as is produced by many tumours, ARP2/3 activation is liable to be widespread with increase frequency in actin rich/ARP2/3 axonal patches, ultimately leading to increased neurite growth and branching." (PMID 29100335, 2017). "Free siRNA suppressed about 21% of NGF mRNA in the tumours compared to the saline control." (PMID 28440296, 2017). "Considering these facts, one could suggest that the antitumor effect of NGF is mediated through the TrkA receptor, activation of which on lymphocytes might be more important than on the tumor cells." (PMID 28878143, 2017).
tumor (continued). "The observation that NGF is a soluble mediator, either released into or produced by the tumor microenvironment, and the fact that NGF is able to act on certain immune-cell activities, would suggest a possible control of cell proliferation towards resistance to cancer survival." (PMID 27439311, 2016). "Although the available observations are consistent with such hypothesis, further studies might be necessary to determine whether a given population of tumor cells is entirely NGF-responsive or contains a proportion of unresponsive cells." (PMID 27439311, 2016). "NGF immunoreactivity has been observed in several tumor tissues and cells." (PMID 27439311, 2016). "Furthermore, tumour spheroids formed by TrkA SH-SY5Y cells in the presence of NGF (100 ng/ml) appeared to be less well formed." (PMID 27551499, 2016). "Evidences that some tumor tissues and their isolated tumor cells can express NGF-receptors and/or store NGF protein suggested the hypothesis that NGF might be involved in tumor cell induction and/or progression." (PMID 27439311, 2016). "Therefore, it is undoubted the great value of understanding the role of growth factors, and merely NGF and NGF-receptors, in tumor developing/progression, as well as the development of tumor growth factor targeted approaches." (PMID 27439311, 2016). "The tumor microenvironment might release high amount of NGF and respond to extracellular NGF in autocrine/paracrine fashion." (PMID 27439311, 2016). "Since Schwann cells around neurons and epithelium rich in neurons express NGF, it is possible that expression of CD271 may predispose tumor cells to PNI." (PMID 25149537, 2014). "Prdm4 was initially cloned as a candidate tumor suppressor gene in human cancers and characterized as a cytoplasmic effector molecule acting downstream of the p75 neurotrophin receptor in response to nerve growth factor signaling." (PMID 23918801, 2013). "In response to a microenvironment with limited amounts of NGF/NT-3, NB tumor cells undergo spontaneous apoptosis, thus disrupting the signals transduced via NGF/NT-3 and their receptors may be a promising therapeutic strategy for the treatment of NB." (PMID 24709709, 2013). "The poor prognosis of the patients with NGF-expressing tumor might be related with the ability of NGF-TrkA signaling to induce chemoresistance." (PMID 24180625, 2013). "In further support of this notion, preventive or late administration of an anti-NGF antibody to mice with PCa cell-induced tumours in the femur significantly attenuated PCIBP by blocking tumour-induced ectopic nerve fibre sprouting and neuroma formation in the bone periosteum." (PMID 23918298, 2013). "Moreover, we have treated PC 12 cells with NGF to evaluate the functional responses of tumor cells differentiated in neuron-like cells." (PMID 22761760, 2012). "In addition, our analysis of NGF production and the TF Egr1 suggest that the production of growth factors in the tumor tissue represents one mechanism whereby a distant tumor can alter the transcriptome of the salivary gland and hence the saliva." (PMID 19517020, 2009). "NGF secreted by tumor cells could also enhance the synthesis and release of some factors including MMPs that promoted cell invasion and metastasis." (PMID 18983683, 2008). "Furthermore, NGF diffuses around tumor tissue and stimulates nerve growth along this concentration gradient, enabling tumor cells to invade nerves and metastasize." (PMID 18983683, 2008). "NGF was highly expressed in tumor cells as well as nerve tissue around the tumor." (PMID 18983683, 2008). "When the expression of NGF by OESCC was compared with clinicopathological data, it became apparent that strong NGF expression correlated with positive lymph node metastasis, positive distant metastasis, poorer tumour differentiation, higher TNM staging, and poorer survival." (PMID 16832412, 2006).